CFTR (CF transmembrane conductance regulator)
Diseases named in the same sentence as CFTR in open-access papers (continued):
Sharing a sentence is not in itself a finding about the gene and the disease.
chronic pancreatitis (continued). "Recently published studies confirmed the association of chronic pancreatitis and CFTR mutations, but until now the underlying mechanisms leading to the development of chronic pancreatitis are poorly understood." (PMID 17204147, 2007). "Additionally, CFTR heterozygosity has been shown to be a strong risk factor for chronic pancreatitis (CP), with one study estimating that CFTR contributed to 24% of idiopathic CP cases." (PMID 40468859, 2025). "Hence, being a compound heterozygote for one severe and one mild CFTR mutation is considered as a strong risk or even causative factor for chronic pancreatitis." (PMID 34065437, 2021). "Chronic pancreatitis results from a complex combination of environmental (e.g. alcohol, cigarettes and occupational chemicals) and genetic factors [e.g. mutation in a trypsin-controlling gene or cystic fibrosis transmembrane conductance regulator (CFTR)]." (PMID 26149296, 2015). "In addition, they focused on the overall contribution of CFTR variants to the aetiology of chronic pancreatitis at the population level." (PMID 23951356, 2013). "Other genes, such as the anionic trypsinogen (PRSS2), the serine protease inhibitor, Kazal type 1 (SPINK1) and the cystic fibrosis transmembrane conductance regulator (CFTR) have been found to be associated with chronic pancreatitis (idiopathic and hereditary) as well." (PMID 17204147, 2007). "The trans-heterozygous association between CFTR mutations in genes involved in the pathways of pancreatic enzyme activation and the pancreatic secretion may be risk factors for the development of recurrent or chronic pancreatitis in patients with CF." (PMID 30134826, 2018). "It is important for asymptomatic CF carriers with specific mutations to be monitored long-term as studies show that CF carriers exhibit slight CFTR dysfunction and are at risk of CRD and, therefore, chronic pancreatitis in heterozygous carriers." (PMID 36832409, 2023). "The aim of the study was to determine the structure of chronic pancreatitis genetic causes in patients living in the European part of Russia by sequencing the entire coding sequence of the PRSS1, SPINK1, CTRC, CFTR, and CPA1 genes." (PMID 37389024, 2023). "Inherited gene variants that impose risk (in genes including PRSS1, SPINK, CTRC, CFTR, and CPA1) typically result in premature activation of digestive enzymes in acinar cells, and have been linked to chronic pancreatitis." (PMID 37452870, 2023). "Recurrent variants of the PRSS1, SPINK1, CTRC, CFTR, and CPA1 genes, contributing to the genetic predisposition to chronic pancreatitis development were identified in a cohort of Russian patients." (PMID 37389024, 2023). "We described the association between V201M CFTR mutation and CRMS diagnosis with a greater risk of developing chronic pancreatitis in Puerto Ricans." (PMID 36832409, 2023). "CFTR-RD include diseases of the pancreas (i.e., acute recurrent or chronic pancreatitis), the male reproductive tract (congenital bilateral absence of the vas deferens) and the upper respiratory tract (i.e., chronic sinusitis)." (PMID 35011616, 2021). "Mutations in the cystic fibrosis transmembrane conductance regulator gene (CFTR) are an established risk factor for cystic fibrosis and chronic pancreatitis." (PMID 33682322, 2021). "Of the 25 patients, 18 (72%) of them were found to have a known genetic mutation (PRSS1, SPINK1, CFTR, CTRC) as the etiology for acute recurrent or chronic pancreatitis." (PMID 33925523, 2021). "The most frequent one in Caucasians is the mutation of the cystic fibrosis transmembrane conductance regulator, CFTR, which causes, among others, a hereditary chronic pancreatitis which is a risk factor for developing PDAC." (PMID 33841132, 2020). "Hereditary pancreatitis can be defined as a patient with recurrent acute or chronic pancreatitis who has a first or second degree relative having similar presentation or one who presents with mutated SPINK1, PRSS1, CFTR, and CTRC genes." (PMID 31588422, 2019).
chronic pancreatitis (continued). "In fact, in addition to CFTR, patients with idiopathic recurrent or chronic pancreatitis have been investigated for other genes related to the premature intra-pancreatic activation of trypsin pathway." (PMID 30134826, 2018). "Cytoplasmic mislocalization of the CFTR chloride channel results in aberrant HCO3- secretion from the pancreatic ducts in chronic pancreatitis." (PMID 23133422, 2012). "Chronic pancreatitis has also been associated with mutations in other genes such as SPINK 1 (serine protease inhibitor Kazal Type I), CFTR (Cystic Fibrosis transmembrane conductance regulator), CTRC (chymotrypsin C)." (PMID 20950468, 2010). "Genes, such as CFTR, PRSS1, and SPINK1, are involved in trypsinogen activation and regulation, with mutations contributing to recurrent acute episodes and progression to chronic pancreatitis." (PMID 39595191, 2024). "The developed genetic panel (PRSS1, SPINK1, CTRC, CFTR, and CPA1 genes) for identification of genetic risk factors of the chronic pancreatitis development and the usage of the next-generation sequencing technology allowed to specify genetic predictors of the disease development in 61% of patients." (PMID 37389024, 2023). "Recurrent-acute or chronic pancreatitis illustrates an accurate phenotype of CFTR dysfunction." (PMID 36832409, 2023). "The impact of chronic pancreatitis on beta-cell function and survival has been stressed by a recent study that suggested an association between exocrine pancreas deficiency and CFRD among CF patients with severe CFTR mutations." (PMID 29222447, 2017). "However, in chronic pancreatitis, trafficking of the CFTR is largely compromised and the protein is largely retained at the cytoplasm of pancreatic ducts." (PMID 23133422, 2012). "To further elucidate the role of CFTR mislocalization in the aberrant ductal HCO3- secretion in chronic pancreatitis, we have examined histology and exocrine functions of patients with autoimmune pancreatitis at the diagnosis and 3 months after maintenance steroid treatment." (PMID 23133422, 2012). "In summary, CFTR mutations alone are not sufficient for the pathogenesis of chronic pancreatitis in most patients and further studies are needed to elucidate the role of CFTR in the pathogenesis of chronic pancreatitis." (PMID 17204147, 2007). "Additionally, this variant has been detected in patients with multiple CFTR-related diseases, including cystic CF, chronic pancreatitis, and congenital bilateral absence of the vas deferens (CBAVD)." (PMID 40433478, 2025). "The observed increase in PDX1 expression of CFTR-KO pancreatic ducts was postulated to be either due to the altered signals from the remodeled pancreatic environment or due to a cell-autonomous change associated with ADM, as often observed in PDX1-positive PDAC caused by chronic pancreatitis." (PMID 39687022, 2024). "The causes of chronic pancreatitis in the patient population of this study were: CFTR and SPINK-1 mutation, non-cancer related obstructive pancreatitis, autoimmune pancreatitis, paraduodenal pancreatitis, hypertriglyceridemia, pancreas divisum morphology, and idiopathic." (PMID 37443666, 2023). "For example, it has been postulated that certain non-CF-causing CFTR variants (e.g., p.Arg75Gln, p.Leu997Phe) leading to a selective, bicarbonate transportation defect in CFTR channel function may be risk factors for chronic pancreatitis." (PMID 34065437, 2021). "Importantly, mutations in CFTR responsible for chronic pancreatitis (CP), but not CF were found to selectively modify the HCO3- permeability of CFTR." (PMID 30618777, 2018). "Hyper activation of CFTR and CaCC proteins may account for such diseases as secretory diarrhea and autosomal dominant polycystic kidney disease, while dysfunction of these proteins may lead to CF, chronic pancreatitis as well as constipation." (PMID 26635857, 2015).
chronic pancreatitis (continued). "Since the cloning of the CFTR gene back in 1989, CFTR has been advocated as a potential therapeutic molecular target for the treatment of several diseases, including CF, chronic pancreatitis, habitual constipation, secretory diarrhea and autosomal dominant polycystic kidney disease." (PMID 26635857, 2015). "In the last decade, several authors identified associations of chronic pancreatitis (idiopathic and hereditary) to other genes, such as the anionic trypsinogen (PRSS2), the Serine Protease Inhibitor, Kazal type 1 (SPINK1) and the cystic fibrosis transmembrane conductance regulator (CFTR)." (PMID 17204147, 2007). "CFTR mutations which associate with chronic pancreatitis (CP), but not with CF, were found to selectively modify the HCO3− permeability of CFTR." (PMID 33430357, 2021). "Those disorders, called CFTR-related disorders (CFTR-RDs), include congenital bilateral absence of vas deferens, acute recurrent or chronic pancreatitis and disseminated bronchiectasis." (PMID 32466381, 2020). "CFTR-RD are milder clinical entities associated with CFTR dysfunction, such as congenital bilateral absence of the vas deferens (CBAVD), disseminated bronchiectasis, chronic pancreatitis or chronic rhinosinusitis." (PMID 25386751, 2014). "When disorders such as chronic pancreatitis occur in these patients, they might be better classified as having a CFTR-related disorder (CFTR-RD), rather than simply being labeled CF carriers, but recent observations may stimulate reassessment of terminology." (PMID 32276344, 2020). "Thus, it is reasonable to consider whether or not the expression of CFTR is compromised in pancreatic duct cells in patients with chronic pancreatitis." (PMID 23133422, 2012).
Infertility (64 papers, 2010 to 2025). "Genetic counseling forms the cornerstone of care once CFTR mutations are identified in an infertile male." (PMID 41009940, 2025). "Genetic screening was done for Y chromosome microdeletions and cystic fibrosis transmembrane conductance regulator (CFTR) gene mutations as possible contributing factors to infertility." (PMID 40313645, 2025). "In Russia and Belarus, studies have been conducted on the spectrum and prevalence of CFTR gene mutations, mainly in infertile men with CF or suffering from CBAVD or CUAVD (unilateral absence of the vas deferens)." (PMID 40724872, 2025). "At the same time, the heterozygous carrier frequency of “severe” CFTR mutations estimated in Russian men with impaired fertility and azoospermia was higher than in the general population, reaching 4.70% in infertile men and 4.82% in men with azoospermia." (PMID 40724872, 2025). "Following clinical suspicion of CBAVD or CF-related infertility, genetic testing is essential to identify underlying CFTR mutations." (PMID 41009940, 2025). "We found variants in genes categorized into isolated infertility (AR and CFTR), reproductive disorders (SRD5A2), and endocrine disorders (LHCGR and CYP21A2)." (PMID 39830005, 2024). "Studies on CFTR gene mutations have shown that infertile men with obstructive azoospermia resulting from the congenital absence of the vas deferens or epididymal obstruction have a higher prevalence of CFTR gene mutations, including D979A, R258G, and M952T." (PMID 38611676, 2024). "The second most common male factor infertility cause is a ductal obstruction or dysfunction, which is produced by CFTR mutations." (PMID 37108159, 2023). "It is expressed at the equatorial segment of the human sperm head and the flagellar midpiece and mutations in the CFTR gene are responsible for infertility and Cystic Fibrosis disease." (PMID 37108159, 2023). "Overall, the CFTR gene mutation and/or 5T allele was found in 88% of Russian infertile men with CBAVD syndrome." (PMID 38003474, 2023). "It should be noted that the L138ins variant was later included in the panel of common CFTR mutations in Russian CF patients, as well as in the panel of CFTR variants in Russian infertile men." (PMID 37510311, 2023). "In our Sanger sequencing study, we found that 51.6% (16 out of 31) of infertile men had CFTR mutations." (PMID 37895049, 2023). "The aim of this study is to determine the frequency of the L138ins variant in the CFTR gene and the CFTR genotypes of carriers in Russian infertile male patients." (PMID 37510311, 2023). "Their allelic frequency (AF) is 0.0005 or more, and the proportion of each variant is 2% or more of all detected pathogenic CFTR gene variants in both Russian infertile men and CBAVD patients." (PMID 38003474, 2023). "It was also shown that three CFTR variants (F508del, CFTRdele2,3(21kb), and L138ins) are prevalent among infertile Russian males, highlighting their significance in genetic population monitoring in Russia." (PMID 38254935, 2023). "According to our data, the L138ins (c.413_415dup; p.(Leu138dup)) variant is one of the most frequent pathogenic variants in the CFTR gene in Russian infertile men." (PMID 37510311, 2023). "The L138ins variant of the CFTR gene was detected previously in infertile men with CBAVD syndrome, however, its frequency in patients with impaired fertility, especially in Russian men with reproductive problems, has not been adequately studied." (PMID 37510311, 2023). "Sanger sequencing of these CFTR mutations was then performed, which further confirmed infertility phenotype co‐segregated with CFTR compound heterozygous mutations in the pedigree." (PMID 37489040, 2023). "Existing literature has demonstrated that over 98% of men with CF and CFTR mutations will experience infertility secondary to defects in mesonephric duct derivatives such as a congenital bilateral absence of the vas deferens (CBAVD)." (PMID 37877879, 2023).
Infertility (continued). "According the results of genetic evaluation of Russian infertile men, the L138ins variant accounted for 6% of all detected variants in the CFTR gene, ranking third in frequency after F508del and CFTRdele2,3." (PMID 37510311, 2023). "Pathogenic variants were detected in 300 (2.49%) of the analyzed alleles of the CFTR gene in 292 (4.84%) of 6033 infertile Russian men." (PMID 37510311, 2023). "In this work, we made an attempt to evaluate the allele frequency (AF) of 12 common CFTR variants in infertile Russian men and healthy individuals from different districts of Russia." (PMID 38254935, 2023). "Before infertility treatment of the men with severe oligozoospermia, genetic counseling and laboratory testing of CFTR gene mutations should be performed to prevent transmission of the relevant gene mutation or CF disease to the next generation." (PMID 35646184, 2022). "There are new mutations, and polymorphisms of M470V and IVS8 poly T CFTR gene in men with very severe oligozoospermia referred to the infertility treatment center in Qom city, Iran." (PMID 35646184, 2022). "We aimed at demonstrating the involvement of the CFTR-ion channel during capacitation of human spermatozoa and, if so, at selecting pathogenic variant-free spermatozoa in infertile men heterozygous for the Phe508del, that can be used in assisted reproduction." (PMID 35115637, 2022). "The need to screen for CFTR mutations in infertile men, such as before intracytoplasmic sperm injection (ICSI), has not been fully explored yet." (PMID 35646184, 2022). "CAVD is a relatively rare condition, but its diagnosis has beyond the problem of infertility, important other medical implications for the patient because of its frequent association with renal anomalies and CFTR mutations." (PMID 32025909, 2021). "Of the 1279 infertile patients tested in our laboratory for the screening of all CF mutations through NGS, 80 (6.3%) were at risk of the transmission of a mutated CFTR gene." (PMID 32357917, 2020). "One infertile Sicilian patient out of 16 was diagnosed as a carrier of one mutated CFTR gene and it was calculated that 1 couple in 256 was at risk of CF transmission." (PMID 32357917, 2020). "A longitudinal CFTR screening of 1279 Sicilian infertile patients for all CFTR mutations sequencing the entire gene by Next Generation Sequencing (NGS) was performed from patient’s blood." (PMID 32357917, 2020). "The present study aimed to evaluate the frequency of common mutations of the CFTR gene including, F508, G551D, G542X, N1303K, and W1282X in Iranian infertile men with NOA and CBAVD using ARMS-PCR technique." (PMID 29986553, 2019). "Evaluating the causes of reduced CFTR expression and infertility in Slc9a3-/- males first requires the precise localization of SLC9A3." (PMID 28384194, 2017). "Fourteen of 80 (17.5%) infertile men due to reduced sperm quality and 3 of 21 (14.3%) men with azoospermia had at least one CFTR mutation (one azoospermic male was a compound heterozygote)." (PMID 28042420, 2017). "Assisted reproduction techniques that are rapidly evolving are increasing the chances for reproduction among infertile men with CFTR mutations along with the increased risk of passing the mutation to the offspring." (PMID 25386751, 2014). "In the 964 infertile couples examined, 132 subjects (69 women and 63 men) were heterozygous for one of the mutations of CFTR, with a carrier occurrence of 6.85%." (PMID 25304080, 2014). "Our results show that CFTR mutations are found in a high percentage of infertile men with obstructive azoospermia (5/22 or 22.7%), which is consistent with the data from other studies." (PMID 25386751, 2014). "This method was used to screen for the presence of the most common CF and CFTR-RD mutations among 369 infertile males divided in two groups (109 patients with and 260 patients without histopathological data) and in 136 fertile controls." (PMID 25386751, 2014).